ATP2B2 (ATPase plasma membrane Ca2+ transporting 2)
Diseases named in the same sentence as ATP2B2 in open-access papers:
ATP2B2 is named in the same sentence as 60 diseases in open-access papers, as found by Europe PMC text mining. Sharing a sentence is not in itself a finding about the gene and the disease. The quoted sentences say what the papers report.
breast carcinoma (20 papers, 2014 to 2025). "Controversially, elevated ATP2B2 expression was found to be associated with poor clinical outcome in breast cancer in another study." (PMID 30352569, 2018). "Moreover, high ATP2B2 expression in breast cancer was found to be associated with specific tumor subtypes." (PMID 30352569, 2018). "While PMCA2 (ATP2B2) was upregulated in HER+ breast cancer tumors, PMCA4 (ATP2B4) was downregulated in colon and prostate cancers, and lymph node metastases in contrast to the relatively high PMCA4 protein level in normal tissues." (PMID 33802790, 2021). "Comparing different breast cancer subtypes we found that ATP2B2 mRNA expression was elevated in basal type cancers, and correlated positively with survival." (PMID 30352569, 2018). "Consistent with the IHC data presented above, there were individual breast cancers with relative high levels of PMCA2 (ATP2B2) in all of the molecular subtypes, this was not seen for PMCA1 (ATP2B1) or PMCA4 (ATP2B4)." (PMID 27148852, 2016). "ATPase plasma membrane Ca2+ transporting 2 (ATP2B2) is a calcium transporter, whose levels correlate with mortality in breast cancers." (PMID 32992741, 2020). "In breast cancer cells upregulated ATP2B1, ATP2B2 mRNA and downregulated ATP2B4 mRNA expressions were described previously." (PMID 30352569, 2018). "Previous in vitro studies showed upregulated ATP2B1 and ATP2B2 mRNA and downregulated ATP2B4 mRNA expression in some breast cancer cell lines." (PMID 30352569, 2018). "In contrast, the expression of the ATP2B1 and ATP2B2 genes was not altered in breast cancer tissues." (PMID 30352569, 2018). "Three distinct datasets displayed significantly lower ATP2B4 mRNA expression in invasive breast cancer tissue samples compared to normal breast tissue, whereas the expression of ATP2B1 and ATP2B2 was not altered." (PMID 30352569, 2018).
deafness (20 papers, 2008 to 2025). An inherited or acquired condition characterized by the complete loss of the ability to hear from one or both ears. "The last is a missense variant in ATP2B2 which has the disease assertion of deafness: autosomal dominant 82 (MIM# 619804)." (PMID 38674358, 2024). "Liposome-mediated gene editing was used to abolish a mutation in gene Atp2b2 and recover hearing in a mouse model of dominant deafness." (PMID 37582836, 2023). "The first mutations identified were in the ATP2B2 gene and have been linked to hereditary deafness in mice and in humans." (PMID 36207321, 2022). "ATP2B2 plays a critical role in intracellular calcium homeostasis, and its mutation is linked to deafness and imbalance." (PMID 34454438, 2021). "The deafness mutations in these mice lie in Atp2b2, which encodes the plasma membrane calcium ATPase 2 (PMCA2)." (PMID 23826306, 2013). "Ablation of the ATP2b2 gene causes deafness and balance disorders in mice, furthermore, various PMCA2 mutations have been linked to hereditary hearing loss in mice and humans." (PMID 22788415, 2012). "The mutation of Atp2b2 may cause deafness and imbalance in mice probably by affecting sensory transduction in stereocilia as well as neurotransmitter release from the basolateral membrane." (PMID 23285140, 2012). "The ATP2B2 gene has recently been implicated in the deafness in 3p- syndrome." (PMID 18974863, 2008). "ATP2B2 (encoded by PMCA in flies), which corresponds to a known genetic interactor of CDH23 that has shown to be implicated in deafness, was also localized ubiquitously throughout Johnston’s organ." (PMID 38412189, 2024). "The profound deafness and ataxia detected in Obl homozygotes is similar to the phenotype of these other known Atp2b2 null mutants." (PMID 18974863, 2008). "Interestingly, a V1143F missense mutation in ATP2B2 gene product, the PMCA2 pump, has been described in an ataxic patient showing no overt signs of deafness." (PMID 36207321, 2022). "In the complete knockout model of the Atp2b2 gene, the absence of PMCA2 leads to significant vestibular dysfunction and severe deafness, further supporting the critical role of PMCA2 in the normal function of hair cells." (PMID 41049429, 2025).
hearing loss (15 papers, 2008 to 2024). "Although a digenic inheritance pattern of hearing impairment has been reported for heterozygous missense variants of ATP2B2 and CDH23, our findings indicate a monogenic cause of hearing impairment in cases with loss-of-function variants of ATP2B2." (PMID 30535804, 2019). "ATP2B2 can be an early warning gene for NIHL, and low expression of ATP2B2 would lead to neurodevelopmental defects of auditory systems and result in hearing loss." (PMID 31886164, 2019). "We checked whether any variant from either ATP2B2 or PCDH15 can contribute to hearing loss in this family in trans with the p.P240L of CDH23 as a modifier or in a digenic fashion, as previously suggested." (PMID 27792758, 2016). "Of note, this person has hearing loss, and POU4F3 has an established relationship with hearing loss; in addition, ATP2B2 has been implicated in hearing loss." (PMID 38674358, 2024). "Among the genes identified via FST and XP-EHH analyses, four are actually associated with hearing loss: CADM1, ESRRB, AKT3, and ATP2B2." (PMID 37570247, 2023). "Up to now ATP2B2 has only been reported as a modifier, or in a digenic mechanism with CDH23 for hearing impairment in humans." (PMID 30535804, 2019).
Ataxia (8 papers, 2008 to 2025). Ataxia refers to impaired coordination of voluntary muscle movement. "For instance, for the ATP2B2 gene, it has been reported that missense and frameshift variants are associated with a spectrum of neurological phenotypes, such as ataxia, dystonia, intellectual disability, autism, seizures, with functional assays, which are in concordance with our reported findings." (PMID 41373895, 2025). "Atp2b2 (encodes PMCA2) knockout mice exhibit overt cerebellar ataxia." (PMID 37374132, 2023). "Very recently, a group of deleterious heterozygous ATP2B2 missense and end-truncating variants were found in 7 patients affected by a variable spectrum of neurological or neurodevelopmental disorders, including dystonia, ataxia, intellectual disability, behavioral symptoms, and seizures." (PMID 41199322, 2025). "In humans, genetic mutations in ATP2B1, ATP2B2 and ATP2B3 gene have been linked with hearing loss, cerebellar ataxia and global neurodevelopmental delay: all of them were found to impair pump activity." (PMID 36207321, 2022). "A heterozygous missense variant in ATP2B2 has recently been associated with ataxia but without HI; the identified variant functionally affected a PMCA2 isoform that is expressed in the cerebellum but not prominently in the inner ear." (PMID 30535804, 2019).
autism (6 papers, 2010 to 2025). Persistent deficits in social interaction and communication and interaction as well as a markedly restricted repertoire of activity and interest as well as repetitive patterns of behavior. "Differentially expressed ATP metabolism genes, such as that of the mitochondrially-encoded ATP synthase membrane subunit 6 (mt-ATP6), Atp2b2 and Abca5, are associated with neuropathologies/neurodegenerations, like Alzheimer’s disease and autism." (PMID 39715923, 2025). "Family-based association studies suggested ATP2B2 as a risk gene for autism in multiple ethnicities." (PMID 30323833, 2018). "Recent studies reported association between ATP2B2 and autism in samples from Autism Genetic Resource Exchange (AGRE) and Italy." (PMID 23620727, 2013). "Results of association between 5 SNPs in ATP2B2 and autism and haplotype analyses in 427 trios of Han Chinese descent." (PMID 23620727, 2013). "First, the aim of this study was to replicate previous positive results of association between ATP2B2 and autism." (PMID 23620727, 2013). "The results of our research indicated that rs3774179 in ATP2B2 was significantly associated with autism (p = 0.013, under an additive model; p = 0.0096, under a dominant model)." (PMID 23620727, 2013). "In this present study, we investigated the association between ATP2B2 polymorphisms and autism in Chinese Han population." (PMID 23620727, 2013). "Considering the genetic heterogeneity in different ethnicities, we performed a family-based association study to investigate the association between ATP2B2 and autism in Chinese Han population." (PMID 23620727, 2013). "The biological functions of ATP2B2 and the positive results of previous association made ATP2B2 become an attractive candidate gene for autism." (PMID 23620727, 2013). "The same method was used to identify ATP2B2 on chromosome 3 in a region in which different autism linkage peaks and association with microsatellite markers have been reported." (PMID 20678243, 2010). "They firstly provided the evidence for a susceptibility gene ATP2B2 for autism." (PMID 23620727, 2013). "In this study, we investigated whether ATP2B2 polymorphisms were associated with autism in Chinese Han population." (PMID 23620727, 2013). "These researches indicated that ATP2B2 might be a predisposing gene for autism." (PMID 23620727, 2013). "Mutation screening of ATP2B2 in children with autism could be performed in further researches." (PMID 23620727, 2013). "Five SNPs (rs35678, rs241509, rs3774180, rs3774179, and rs2278556) in ATP2B2 were genotyped in 427 autism trios (1281 individuals)." (PMID 23620727, 2013). "We performed a family based association study between five SNPs (rs35678 in exon, rs241509, rs3774180, rs3774179, and rs2278556 in introns) in ATP2B2 and autism in 427 autism trios of Han Chinese descent." (PMID 23620727, 2013). "Previous studies have shown that variants in SLC25A12, EN2, ATP2B2 and PITX1, have an association with autism." (PMID 20678243, 2010). "In conclusion, our present results provided evidence that ATP2B2 might be relevant to the etiology of autism." (PMID 23620727, 2013). "Therefore, our research did not explore the association between SNPs in promoter region and 3′ untranslated region in ATP2B2 with autism." (PMID 23620727, 2013). "Our research suggested that ATP2B2 might play a role in the etiology of autism in Chinese Han population." (PMID 23620727, 2013). "For example, dysfunction of ATP2B2 might lead to decreased expression of metabotropic glutamate receptor and aberrant signaling in Purkinje neurons, resulting in functional deficits of cerebellum, which usually can be detected in autism." (PMID 23620727, 2013). "Previous GWAS did not detect the association between ATP2B2 and autism." (PMID 23620727, 2013).
schizophrenia (4 papers, 2018 to 2025). A major psychotic disorder characterized by abnormalities in the perception or expression of reality. "In the SCHEMA, the gene ATP2B2 shows highly suggestive evidence for deleterious missense variants in schizophrenia cases (p = .000072)." (PMID 37881554, 2023). "Additionally, the variant in ATP2B2 identified here was observed only in 1 schizophrenia sample in the SCHEMA dataset." (PMID 37881554, 2023). "Given how rare these variants are in the population, large sample sizes are required in the discovery analysis to achieve statistical significance, and future work by the SCHEMA consortium may implicate ATP2B2 as a schizophrenia risk gene." (PMID 37881554, 2023). "A previous study also suggested ATP2B2 could confer risk to schizophrenia." (PMID 30323833, 2018). "We further pinpointed two genes ATP2B2 (rs9879311, P = 2.77 × 10−6) and NOS1 (rs2293052, P = 1.24 × 10−6), which were closely connected to the NMDAR interactome and showed strong associations with schizophrenia risk." (PMID 30323833, 2018).
autism spectrum disorder (3 papers, 2019 to 2023). A spectrum of developmental disorders that includes autism, and Asperger syndrome. "Two de novo truncating variants in ATP2B2 have been identified in a study on autism spectrum disorders (ASD), which is a complex disorder." (PMID 30535804, 2019). "Additionally, damaging de novo variants in ATP2B2 have been shown to be significantly enriched in autism spectrum disorder cases compared with unaffected siblings in a Japanese cohort." (PMID 37881554, 2023). "Genome-wide association studies (GWASs) have demonstrated various risk loci for ASD such as FOXP1 at 3p13, ATP2B2 at 3p25.3 [Autism Spectrum Disorders Working Group of the Psychiatric Genomics Consortium, 2017(Autism Spectrum Disorders Working Group of The Psychiatric Genomics Consortium., 2017)]." (PMID 35655651, 2022).
Stroke (3 papers, 2012 to 2019). Sudden impairment of blood flow to a part of the brain due to occlusion or rupture of an artery to the brain. "Ca2+-ATPase-encoding Atp2b2 plays a major role in clearing Ca2+ from the neuronal cytoplasm and was downregulated after stroke." (PMID 23251410, 2012). "For stroke, Apcdd1, Atp2b2, Axin2, ITIH-5 and Slc1a1 are specifically expressed in brain vasculome." (PMID 23285140, 2012).
epilepsy (2 papers, 2023 to 2025). A brain disorder characterized by episodes of abnormally increased neuronal discharge resulting in transient episodes of sensory or motor neurological dysfunction, or psychic dysfunction. "Both ATP1A1 and ATP2B2 have been previously linked to neurodevelopmental disorders, including phenotypes such as intellectual disability, epilepsy, and ASD." (PMID 40836247, 2025). "Expression levels of SLC1A1, SLC25A12, ATP2B2 and their related lncRNAs were significantly different between patients with epilepsy and healthy subjects." (PMID 37865723, 2023).
leukemia (2 papers, 2014). A malignant (clonal) hematologic disorder, involving hematopoietic stem cells and characterized by the presence of primitive or atypical myeloid or lymphoid cells in the bone marrow and the blood. "Furthermore, cryptic genomic alterations involving leukemia-related genes, such as ATP2B2, ANGPT1, ETV6 and RB1CC1, were inferred in the level of array CGH and confirmed by FISH." (PMID 25120648, 2014). "The candidates ATP2B2, PARP8 and TAS1R3 have previously not been functionally linked to leukemia." (PMID 24517546, 2014).
prostate carcinoma (2 papers, 2014 to 2021). A carcinoma that arises from epithelial cells of the prostate gland. "The model was able to identify prostate cancer associated SNPs that either map to a cancer specific genes such as CRR9, TERT, ATP2B2, ARL9, and AGBL4 and/or with regulatory effects." (PMID 24651484, 2014).
acute myocardial infarction (1 paper, 2022). Necrosis of the myocardium, as a result of interruption of the blood supply to the area. "For example, hsa_circ_0023461 might act as a hsa-miR-589-5p sponge and play a regulatory role in acute myocardial infarction by influencing the expression of ATP2B2." (PMID 35872921, 2022).
anaphylaxis (1 paper, 2019). An acute hypersensitivity reaction that occurs from exposure to an allergen. "This approach identified several genes that are associated with aging (ATP2B2, CAV3, CNTN3, CTNNA2, GRID2), inflammation (ATP2B2, CAV3, RAD18, KBTBD8), vascular permeability (SFXN5, RAD18) and anaphylaxis (CAV3, RAD18, CTNNA2, ATP2B2 and GRID2)." (PMID 31701027, 2019).
colitis (1 paper, 2022). Inflammation of the colon. "Western blot analysis of the colon samples confirmed a reduction in plasm membrane Ca2+ pump proteins (PMCA), encoded by Atp2b1, Atp2b2, Atp2b3, and Atp2b4 and recognized by the same antibody, in colitis mice, which was rescued by BBR." (PMID 36528592, 2022).
COVID-19 (1 paper, 2024). A disease caused by infection with severe acute respiratory syndrome coronavirus 2. "Furthermore, there were undetectable expression levels of ATP2A1, ATP2A3, ATP2B2, and ATP2B3 in the lungs of both COVID-19 patients and controls (Fig. EV1G)." (PMID 38816514, 2024).
hepatoma (1 paper, 2021). "Regarding the less abundant isoforms, Atp2b2 showed a significant decrease in tumor cells, while Atp2b3 showed an increasing but not significant trend in hepatoma cells." (PMID 34737944, 2021).
Nephropathy (1 paper, 2023). A nonspecific term referring to disease or damage of the kidneys. "Tag-SNPs captured by SLC17A3 rs942379 variant additionally impacts the expression of BTN3A2 in glomerulus and those captured by TATDN2 rs394558 variant combinedly affects the expression of ATP2B2 in glomerulus further elucidating its role in nephropathy related traits." (PMID 37696853, 2023).
neuroblastoma (1 paper, 2017). Neuroblastoma (NB) is the most common solid, extracranial childhood tumor. "Under these conditions only two cell lines expressed detectable levels of Atp2b2, OC-1 cells from the immortomouse organ of Corti and the N2A neuroblastoma cell line." (PMID 28532435, 2017).
Obesity (1 paper, 2021). Accumulation of substantial excess body fat. "In this study, we respectively constructed specific miRNA-mRNA regulatory networks of obesity-related ccRCC for both VAT and SAT, and 3 RNA pairs (i.e. hsa-miR-182&ATP2B2, hsa-miR-532&CDH2 in VAT; and hsa-miR-425&TFAP2B in SAT) were finally screened out." (PMID 34621242, 2021).
cancer (16 papers, 2014 to 2025). A tumor composed of atypical neoplastic, often pleomorphic cells that invade other tissues. "Several previous studies support the findings of the present study, including the link between ATP2B2 and ATP2A3 in cancer, as well as the hypothesis that ATP2B3 might serve as a possible cancer biomarker." (PMID 34684111, 2021).
tumor (12 papers, 2014 to 2025). "For five additional candidate targets including ITGA3 (n = 11), PCDH7 (n = 6), SLC39A10 (n = 6), ATP2B2 (n = 5), and HTR2B (n = 5), a quasi H − score ≥ 150 in at least 5 tumor types was also found." (PMID 33490264, 2021).
ATP2B2 also shares sentences with these, for which no sentence is quoted: Hearing impairment (6 papers); cerebellar ataxia (5); 3p- syndrome (2); Alzheimer disease (2); breast tumor (2); Dystonia (2); Intellectual disability (2); mastitis (2); multiple sclerosis (2); X-linked cerebellar ataxia (2); arrhythmogenic right ventricular cardiomyopathy (1); atrial septal defect (1); autosomal dominant non-syndromic hearing loss (1); benign tumors (1); Cirrhosis (1); colon cancer (1); dilated cardiomyopathy (1); ductal carcinoma in situ (1); experimental autoimmune encephalomyelitis (1); gastric carcinoma (1); Huntington disease (1); hypertrophic cardiomyopathy (1); Hypocalcemia (1); infection (1); liver (1); maturity-onset diabetes (1); Meconium ileus (1); neurodegenerative disease (1); neurodevelopmental disorder (1); nicotine addiction (1).
A further 9 diseases each share a sentence with ATP2B2 in 1 paper.